AVP (arginine vasopressin)
Diseases named in the same sentence as AVP in open-access papers (continued):
Sharing a sentence is not in itself a finding about the gene and the disease.
heart failure (continued). "Patients with cardiovascular pathologies, predominantly heart failure, but also myocardial infarction and arterial hypertension, present elevated plasma AVP levels." (PMID 34768894, 2021). "Population-based data have shown elevated plasma AVP levels and its surrogate marker copeptin in various types of heart failure, acute myocardial infarction, diabetes development, and hypertension." (PMID 34768894, 2021). "Specifically, rats with heart failure produced by an overloading of the left ventricle manifested significantly elevated AVP levels in the PVN, the SON, the parafascicular nucleus, and the NTS." (PMID 34768894, 2021). "Arginine vasopressin (AVP) is elevated in patients with heart failure, and the increase in the AVP concentration in plasma is positively correlated with disease severity and mortality." (PMID 32489586, 2020). "Studies have shown that AVP levels are significantly elevated in the plasma of patients with heart failure and AVP can induce myocardial fibroblast proliferation and promote myocardial fibrosis through its V1a receptor." (PMID 31053625, 2019). "The precise mechanism for sensing and signalling of osmotic disturbances and thus blood plasma volume has important implications in heart failure as recent evidence would suggest AVP modulation of sympathoexcitibility is impaired in disease." (PMID 30078222, 2018). "In particular, arterial under-filling, as observed during heart failure, stimulates AVP secretion via baroreceptors in the carotid sinus and the aortic arch." (PMID 29100503, 2017). "Nephrotic syndrome is similar to heart failure and liver cirrhosis with regard to increased AVP levels and water retention." (PMID 26903868, 2016). "Elevated levels of AVP as in the syndrome of inappropriate antidiuretic hormone secretion (SIADH), late stage heart failure, and liver cirrhosis cause excessive water retention." (PMID 26903868, 2016). "In contrast to heart failure and liver cirrhosis the nephrotic syndrome shows an “escape” from AVP in the renal collecting ducts." (PMID 26903868, 2016). "As for patients with increased ECFV, a category largely dominated by conditions related to heart failure or cirrhosis, “effective hypovolemia” provides the grounds for increased AVP secretion." (PMID 26553121, 2015). "First, the physiological control of AVP release, and inappropriate release of AVP in heart failure are described." (PMID 26239456, 2015). "In several animal models of low-output and high-output cardiac failure and in congestive heart failure in humans, it has been demonstrated that plasma AVP, renin activity, aldosterone and norepinephrine are significantly increased." (PMID 26239456, 2015). "This indicates a potentially deleterious effect of AVP in patients with heart failure or cardiogenic shock due to impaired coronary perfusion." (PMID 18291025, 2008). "Arginine vasopressin (AVP) plays a significant role in the pathophysiology of heart failure." (PMID 41179034, 2025). "New biomarkers gaining importance in heart failure management include mid-regional pro adrenomedullin (MR-proADM) and copeptin (stable C-terminal pro-peptide fragment of arginine vasopressin), indicating neurohormonal activation, ST2, and Galectin-3, indicating myocardial remodeling." (PMID 38248885, 2024). "In addition to these two well-established pathways, the arginine vasopressin (AVP) system is also thought to be a major neurohormonal process that plays an integral role in the progression of heart failure." (PMID 37508636, 2023). "Experimental studies show that the neurogenic stress provokes the release of AVP, and that the stimulation of V1aR by AVP plays a significant role in the potentiation of the magnitude of the cardiovascular and behavioral responses to stress in hypertension and heart failure." (PMID 36430892, 2022). "Among the complex neurohormonal activation pathways, AVP plays an important role in heart failure." (PMID 35327416, 2022).
heart failure (continued). "An increase in hypothalamic MNC excitability could lead to increased AVP release and the well documented sympathoexcitation observed in heart failure animals." (PMID 30078222, 2018). "However, recent studies of heart failure in rat models revealed increased AQP2 protein abundance even in the presence of normal AVP and unchanged plasma sodium levels." (PMID 26903868, 2016). "Theoretically, elevated plasma AVP may act on V1a receptors and mimic blood pressure control, but there is no clinical evidence for modulating blood pressure via V1a receptors in heart failure patients." (PMID 26239456, 2015). "In the SOLVD (Studies of Left Ventricular Dysfunction), subjects with left ventricular dysfunction had significantly higher plasma arginine vasopressin levels compared to controls, and arginine vasopressin levels were highest in the subjects with overt heart failure." (PMID 16737547, 2006). "Since AVP levels in patients with heart failure and left ventricular (LV) dysfunction are often elevated, it is hypothesized that AVP might contribute to circulatory response in patients with heart failure and play a role in the development and progression of heart failure." (PMID 33805177, 2021). "Specifically, we discuss the positive and negative consequences of the interaction of AVP and steroid hormones in the development of hypertension and heart failure." (PMID 39000501, 2024). "Moreover, heart failure induced renal hypoperfusion activates RAAS, sympathetic nervous system, and arginine vasopressin that leads to fluid retention, increased preload, and worsening heart failure." (PMID 37438747, 2023). "It has been postulated that AVP release stimulus is more shifted to a non-osmotic trigger compared to an osmotic trigger in heart failure." (PMID 37508636, 2023). "Background and objectives: Plasma arginine vasopressin (P-AVP) is regulated by the non-osmotic pathway in patients with heart failure (HF) and reduced ejection fraction." (PMID 32268535, 2020). "The renin-angiotensin system and the nonosmotic release of arginine vasopressin (AVP) are increased in cardiac failure." (PMID 26074997, 2015). "The pathophysiology of heart failure involves intricate neurohormonal mechanisms, including the activation of the sympathetic nervous system, the renin-angiotensin-aldosterone system, and the release of various hormones such as antidiuretic hormone (ADH), also known as arginine vasopressin (AVP)." (PMID 41179034, 2025). "Additionally, patients with heart failure were sensitive to blood sodium concentrations, with even normal levels stimulating the release of arginine vasopressin (AVP)." (PMID 32500625, 2020). "In humans with heart failure and in several animal models of heart failure, RAAS system activity, the non-osmotic release of AVP and the expression level and membrane localization of AQP2 are significantly increased." (PMID 26903868, 2016).
diabetes (56 papers, 2010 to 2026). "Several large longitudinal cohorts investigated the association of AVP or copeptin with the risk of diabetes development." (PMID 40428796, 2025). "CPP, a marker substituting for the homologous precursor of arginine vasopressin, is closely linked with metabolic conditions such as diabetes mellitus, hyperlipidemia, and hypertension." (PMID 40308270, 2025). "Population-based studies have identified several single nucleotide polymorphisms in the AVP, V1aR and V1bR genes that are associated with insulin resistance, hyperglycemia, obesity and diabetes development." (PMID 40428796, 2025). "For example, there are several studies showing associations between increased copeptin level (a surrogate measure of AVP, and therefore a measure of hydration status) and the risk of diabetes." (PMID 38892576, 2024). "It should also be noted that experiments on rats with streptozotocin-induced diabetes mellitus associated with hyperglycemia and hyperosmolality disclosed elevated AVP secretion and reduced V1aR mRNA expression in the liver." (PMID 39769071, 2024). "Arginine vasopressin (AVP) is a pituitary gland peptide which was proven to be related to CV risk factors such as abdominal obesity and diabetes." (PMID 37629496, 2023). "Peripheral AVP has been recognized as a risk factor for type 2 diabetes, but the role of hypothalamic AVP in diabetes is still being explored." (PMID 31912136, 2020). "Renal dysfunction has been associated with an increased risk of stroke and AVP is known to be associated with declining kidney function in patients with diabetes." (PMID 27312697, 2016). "Diabetes mellitus is associated with a significant polyuria and natriuresis, as well as increased plasma aldosterone and anti-diuretic hormone arginine vasopressin (AVP) levels." (PMID 25346724, 2014). "Taken together, an ameliorated collateral AVP responsiveness of cirrhotic rats with diabetes is, at least partly, associated with Gα down-regulation." (PMID 23874439, 2013). "Additionally, epidemiological and clinical studies have also suggested the connection between elevated AVP levels and the risk of hyperglycemia, diabetes and metabolic syndrome development." (PMID 40428796, 2025). "Their result suggested that targeting the AVP system might have beneficial effects on cardiovascular disease mortality and stroke risk in older men with diabetes." (PMID 39777314, 2024). "Subsequently, it has been shown that copeptin, the stable carboxy-terminal portion of pro-arginine vasopressin secreted in equimolar amounts with AVP, is independently associated with hyperinsulinemia, the development of diabetes mellitus, and the metabolic syndrome." (PMID 35656391, 2022). "Two decades later, medical professionals hypothesized that the excess water loss (i.e., polyuria) observed in people with type 2 diabetes mellitus resulted from decreased secretion of AVP." (PMID 30563134, 2018). "Results obtained in rodent models of diabetes suggest that the underlying mechanism may be that AVP leads to hyperfiltration and then to albuminuria and glomerulosclerosis." (PMID 28638629, 2017). "Excreting a low volume of concentrated urine appears to have costs that are both direct (i.e., faster decline in GFR and incidence of kidney stone recurrence) and indirect (i.e., association between increased circulating AVP and glycemic control, diabetes, hypertension, and ADPKD)." (PMID 25866433, 2015). "While AVP appeared to improve glucose tolerance in animal experiments, recent findings have revealed an independent association between plasma copeptin, which is a stable C-terminal portion of pre/pro-vasopressin peptide and is used for a surrogate marker for circulating AVP, and risk of diabetes." (PMID 33905792, 2021).
diabetes (continued). "Based on these findings, it is proposed that the patient’s CDI may have resulted from diabetes mellitus-associated microvascular injury, which likely compromised blood supply to the hypothalamic–pituitary axis, thereby disrupting the synthesis and secretion of AVP." (PMID 41211065, 2025). "The stimulatory effect of insulin on AVP secretion was confirmed in several other species and in patients with type 1 diabetes mellitus." (PMID 39769071, 2024). "Both experimental and clinical data indicate that inappropriate interactions of AVP and insulin play an important role in the development of insulin resistance in obesity and diabetes mellitus." (PMID 39769071, 2024). "The cooperation between these peptides and insulin is emphasized, drawing attention to the aberrant interactions of RAS and AVP with insulin in diabetes mellitus and other metabolic disorders." (PMID 38279313, 2024). "The effectiveness of the stimulation of glucagon release by AVP appears to be significantly impaired in patients with type 1 diabetes mellitus." (PMID 38279313, 2024). "It has been proposed that people who drink less water have a greater chance of developing diabetes and this is related to higher AVP circulating levels." (PMID 36773648, 2023). "On the other hand, hypothalamic AVP expression in rats is also increased with the onset of diabetes mellitus, suggesting a normal and pathophysiological effect of AVP in metabolism regulation." (PMID 34436435, 2021). "In human, the mean basal plasma AVP level in the patients with diabetes mellitus was significantly higher than control subjects." (PMID 33905792, 2021). "In humans, the metabolic effects of AVP are unclear, however, several investigations have also suggested a link between AVP and metabolic disorders, such as obesity and diabetes." (PMID 34436435, 2021). "Further, evidence suggests that both a low daily TWI and/or elevated plasma AVP influence the development and progression of metabolic syndrome, diabetes, obesity, chronic kidney disease, hypertension and cardiovascular disease." (PMID 32210168, 2020). "Notably, SGLT2 inhibitors promote glycosuria by lowering the renal glucose reabsorption threshold, whereas AVP promotes water reabsorption through stimulation of V2 receptors, and increased levels of AVP appear to limit glucose-induced water loss in patients with diabetes." (PMID 27312697, 2016). "The totality of findings supports a potential role of the AVP system in the pathogenesis of diabetes." (PMID 26158609, 2015). "This study proposes that people who drink less water have a greater chance of developing diabetes related to higher AVP levels." (PMID 25853137, 2015). "Prior studies suggested a role for the arginine vasopressin (AVP) system in the pathogenesis of diabetes." (PMID 26158609, 2015). "The role of AVP in pathogenesis of both diabetes mellitus and abdominal obesity was described before; however, it is still not well known." (PMID 24375010, 2014). "Diabetes diminished the portal-systemic collateral vascular response to AVP in rats with BDL-induced cirrhosis, probably via V2 receptor up-regulation and Gα proteins down-regulation." (PMID 23874439, 2013). "In conclusion, cirrhotic rats with diabetes exert poorer portal-systemic collateral AVP response than normoglycemic cirrhotic rats." (PMID 23874439, 2013). "This study investigated the impact of diabetes or glucose application on portal-systemic collateral vasoresponsiveness to arginine vasopressin (AVP) in cirrhosis." (PMID 23874439, 2013). "It is hypothesized that diabetes mellitus-related microvascular injury may impair the blood supply to the hypothalamic–pituitary axis, thereby disrupting the synthesis and secretion of AVP." (PMID 41211065, 2025). "There is evidence that the insulin-dependent release of AVP may be markedly dysregulated in diabetes mellitus and obesity." (PMID 38279313, 2024).
diabetes (continued). "Studies conducted on AVP-deficient Brattleboro rats that were also suffering from diabetes mellitus showed that AVP does not play a significant role in the regulation of the release of HPA hormones during acute stress." (PMID 39000501, 2024). "The stimulatory effect of insulin on AVP secretion and the potency of insulin to reduce AVP-induced hyperglycemia are diminished in diabetes mellitus and insulin resistance, which may result from inappropriate generation of gasotransmitters and free radicals." (PMID 39769071, 2024). "Epidemiological studies have explored the correlation between AVP and diabetes." (PMID 39217353, 2024). "In this respect, it has been shown that isolated coronary vessels of control female rats and female rats with streptozotocin-induced diabetes are less sensitive to the vasoconstrictive action of AVP than the corresponding vessels of control and diabetic male rats." (PMID 38279313, 2024). "It was also shown that although in patients with diabetes mellitus, the insulin-dependent hypoglycemia elevated blood vasopressin concentration, the release of AVP was markedly smaller in diabetic patients with asymptomatic insulin-induced hypoglycemia than in the healthy subjects." (PMID 39769071, 2024). "This may help explain the reported observations of elevated plasma AVP (copeptin) levels in patients with diabetes." (PMID 35656391, 2022). "Many clinical studies have suggested that high blood AVP levels, or high blood copeptin levels, could contribute to type 2 diabetes mellitus and metabolic syndromes." (PMID 33905792, 2021). "AVP levels were indirectly measured in some studies, perhaps explaining the discrepancy, and raising a question about whether copeptin is an appropriate surrogate for AVP in diabetes." (PMID 33905792, 2021). "Future studies are required to explore whether elevated copeptin, as a sensitive marker for AVP secretion, is just a risk marker or a potentially modifiable risk factor for CVD mortality and stroke in diabetes." (PMID 27312697, 2016). "Targeting the arginine vasopressin system might have beneficial effects on CVD mortality and stroke risk in older men with diabetes." (PMID 27312697, 2016). "In this study of older men, elevated plasma copeptin, a surrogate marker for plasma AVP release, was significantly associated with a higher risk of incident diabetes independent of established diabetes risk factors." (PMID 26158609, 2015). "Several lines of evidence support a role for AVP in the pathogenesis of diabetes." (PMID 26158609, 2015). "The findings suggest a potential role of the AVP system in diabetes." (PMID 26158609, 2015). "We hypothesized that diabetes and/or glucose application may elicit changes of collateral vasoresponsiveness to AVP in cirrhotic rats." (PMID 23874439, 2013). "The present study indicates that diabetes diminishes the portal-systemic collateral AVP response in cirrhotic rats, which may be related to V2 receptor up-regulation and Gα proteins down-regulation." (PMID 23874439, 2013). "We describe a 38-year-old woman with early-onset insulin-requiring, autoantibody-negative diabetes, progressive visual loss due to optic atrophy, bilateral sensorineural hearing loss, secondary amenorrhea with hyperprolactinemia, and arginine-vasopressin (AVP) deficiency." (PMID 42093864, 2026). "Thus, genetic variance of AVP and its receptors might contribute, at least in part, to develop metabolic disorders, including obesity, overweight, and type 2 diabetes mellitus." (PMID 33905792, 2021). "AVP also appears to play a role in glucose homeostasis, insulin resistance and diabetes mellitus (DM)." (PMID 32062761, 2020). "As we have previously found that high activity of the AVP system is related to components of the metabolic syndrome including both diabetes and hypertension we here aimed to test whether a high salt intake would alter activity of the AVP system and, if that were the case, in which direction." (PMID 25405024, 2014).
diabetes (continued). "Similarly, in AVP-deficient Brattleboro rats with streptozotocin-induced diabetes, desmopressin infusion normalized water consumption and body weight, yet had no impact on diabetes-associated alterations of the HPA axis or glucose metabolism." (PMID 40428796, 2025). "In this context, our results strongly suggest that RAGE activation participates in the hypertensive state in diabetes by also amplifying VSMC responses to vasopressive hormones, such as AVP." (PMID 26248341, 2015). "Even though AVP induces insulin secretion, using high concentrations of AVP to treat diabetes is not advisable due to its many receptors and functions." (PMID 39217353, 2024). "This study aimed to examine the association between copeptin (a surrogate marker of arginine vasopressin) and incident stroke, CHD and cardiovascular mortality in older men with and without diabetes." (PMID 27312697, 2016). "However, out data showed that D-glucose perfusion did not modify AVP responsiveness in cirrhotic rats with or without STZ-induced diabetes." (PMID 23874439, 2013). "Moreover, the state of hyperglycemia following stroke (as a result of direct post-stroke hyperglycemia or exacerbation of pre-existing diabetes) may increase the number of AVP-expressing neurons in PVN and SON, resulting in increased release of AVP during stroke." (PMID 36768443, 2023).